IL6 (interleukin 6)
Diseases named in the same sentence as IL6 in open-access papers (continued):
Sharing a sentence is not in itself a finding about the gene and the disease.
Arthritis (continued). "Their results showed that piperine could suppress the expression of IL6 and matrix metalloproteinase (MMPs), and therefore reduce the synthesis of prostaglandin E2, the symptoms of arthritis, and inflammatory areas in the ankle joint." (PMID 39319351, 2024). "At the dose of 200 mg/kg, YEO treatment reduced interleukin-6 (IL-6) levels and cartilage destruction in the zymosan-induced arthritis model, and reduced edema formation and mechanical hyperalgesia in the model of persistent inflammation (21 days) induced by complete Freund’s adjuvant (CFA) in mice." (PMID 39194751, 2024). "Using recordings from spinal cord neurons, we were able to show that spinal EGF signaling comes into play when the spinal cord is stimulated by IL-6-trans-signaling, a mechanism involved in the generation of spinal hyperexcitability, e.g., during the development of arthritis." (PMID 39000275, 2024). "The cytokine/chemokine milieu suggests that disease severity in post-CHIKV arthritis is driven by processes such as IL-6-mediated inflammation and TNF-mediated T-cell chemotaxis, in addition to an immunomodulatory response from IL-10 in an attempt to regulate immune-related damage." (PMID 38507338, 2024). "The finding of elevated SAA in the liver by inflammatory arthritis, specifically by IL-6 and IL-1β, raised the intriguing hypothesis that with the presence of arthritis, the liver takes an active part in exacerbating disease progression by secreting SAA." (PMID 38426494, 2024). "Additionally, we measured the levels of TNF-α, IL-1β, and IL-6 in the OA joint by ELISA measurements, which are known to be elevated with the onset of arthritis and correlate with its severity." (PMID 39076894, 2024). "Excessive production of IL‐6 in arthritis can activate and proliferate inflammatory T cells and B cells, triggering immune reactions and autoantibody production, thereby worsening arthritis." (PMID 39554315, 2024). "The significance of IL-6 is clearly displayed by previous findings that IL-6-deficient mice display little or no antigen-induced arthritis." (PMID 38856919, 2024). "Rather, the SAA/NFAT5 axis may require an initial priming of synovitis repeatedly secreting a high amount of IL-1β and/or IL-6 so as to establish a chronic form of arthritis." (PMID 38426494, 2024). "Injection of IL-6 into the affected joints also almost completely reversed arthritis reduction by NFAT5 deficiency, suggesting that IL-6, in addition to CCL2, mediates the progression of SAA/NFAT5 axis–dependent arthritis." (PMID 38426494, 2024). "In addition, SIN improved arthritis in rats by inhibiting pro-inflammatory cytokines IL-1β and IL-6, inhibiting MMP-2/-9, and increasing TIMP-1/-3." (PMID 38276618, 2024). "The variable abundances of IL6-producing cell subsets across patient synovia may shape the differential therapeutic responses of arthritis patients to anti-IL6 therapies or JAK inhibitors." (PMID 38832018, 2024). "In addition, the serum levels of IL-1β, TNF-α, and IL-6 showed a significant decrease for rats fed dietary OTMs, which alleviated arthritis symptoms in rats." (PMID 39330501, 2024). "In light of the effects of BSR/5-Loxin® on inflammatory mediators and enzymes in these studies on animal diseases, it is interesting that exogenously added SPMs reduced the levels of pro-inflammatory cytokines like TNF-α and IL-6 as well as of MMPs and nitric oxide in comparable arthritis models." (PMID 38239198, 2023). "IL-6 is a well-known pro-inflammatory cytokine, a common target of biologic therapy, with multiple functions including antibody production and hematopoiesis, and it plays a detrimental role in arthritis by promoting osteoclast formation and bone resorption." (PMID 37277817, 2023).
Arthritis (continued). "Other authors observed that the treatment with hydroethanolic extract of the leaves of S. terebinthifolius caused a reduction in the concentration of IL-6 and TNF-α in a model of arthritis induced by zymosan in mice, which corroborates the effect observed in our study." (PMID 37639162, 2023). "In the mouse CIA model (a preclinical model of RA), its derivative TIM1c, administered in oral form, showed a similar effect to Etanercept, alleviating RA signs and arthritis, as well as a reduction in inflammatory factors IL-1ß and IL-6, with better anti-inflammatory activity." (PMID 37859999, 2023). "Bioactive particles such as HAMA microspheres, modified liposomes, and chitosan-modified nanoparticles can be used as gene delivery vectors (IL-6-siRNA, TNF-α, etc.)to treat arthritis and bone loss by decreasing the expression of inflammatory factors in RA and OA." (PMID 37064239, 2023). "Similarly, IL-18R alpha-deficient mice exhibited an attenuated form of arthritis with reduced synovial CD4 T cell and macrophage infiltration as well as lower serum levels of IL-6, IL-18, TNF-α and IFN-γ as compared to WT mice." (PMID 37415987, 2023). "Indeed, NF-kB associates with the promoter region of E2F2, and activated E2F2 subsequently binds to the promoter of IL-6, which in turn leads to the development of arthritis." (PMID 37293258, 2023). "Similarly, recent literature reported that Nec-1 significantly reduced the levels of TNF-α, IL-1β, and IL-6 and reduced the severity of arthritis in rats." (PMID 37446099, 2023). "Moreover, we found that in isolated arthritis, calprotectin and IL-6 appeared to demonstrate greater specificity than in the connective pattern." (PMID 38137631, 2023). "Following 13.6 mg/kg of treatment, it was observed that pomegranate extract could lower interleukin-6 (IL-6) and interleukin-1 beta (IL-β), consequently decreasing the arthritis incidence." (PMID 35757262, 2022). "Moreover, the CFA + MTX-GNPs group showed significant inhibition of serum IL-6 by 36.52% when compared to the CFA-arthritis group." (PMID 36678557, 2022). "Moreover, IL-6, as well as sIL-6Rα, induced long-lasting robust sensitization of joint nociceptors to mechanical stimuli in an experimental arthritis model." (PMID 35909446, 2022). "Likewise, D-carvone presented anti-arthritic activity against complete Freund’s adjuvant-induced arthritis in rats via significantly modulating the levels of inflammatory cytokines (IL-6, IL-1β, and TNF-α)." (PMID 36294936, 2022). "Apart from IL-1β, also IL‐6 plays an arthritis- and inflammation-mediating role." (PMID 34142176, 2022). "7-HF has been found to inhibit lipopolysaccharides-induced inflammation via attenuating the production of NO, prostaglandin E2, PGE2, tumor necrosis factor α, TNF-α, and interleukin 6, IL-6, which are mediators in the inflammatory processes accompanying several diseases such as arthritis." (PMID 36559299, 2022). "In addition, MIF inhibitors can inhibit the activation of macrophages and the expression of inflammatory factors, such as NO, TNF-α and IL-6, which can significantly improve arthritis and articular cartilage injury in rats." (PMID 35395782, 2022). "Additionally, the CFA + MTX-GNPs gel formula group experienced significant inhibition of serum IL-6 by 22.52% compared to the CFA-arthritis group." (PMID 36678557, 2022). "IL-6 is among the main factors converting FoxP3+ Treg cells to the Th17 phenotype and is often found in high concentration in the synovium of patients with arthritis." (PMID 36389710, 2022). "However, excessive IL‐6 is involved in the pathological process of arthritis, gastrointestinal inflammation, neuroinflammatory diseases, and so on." (PMID 37786887, 2022). "The in vivo results showed that corilagin significantly reduced paw swelling and arthritis score and inhibited joint erosion and the infiltration of inflammatory cells; pro-inflammatory cytokines were also inhibited at the serum level (IL-6, TNF-α, IL-1β, and IL-17)." (PMID 36364420, 2022).
Arthritis (continued). "In vivo, BHA alleviated paw and joint swelling, decreased inflammatory cell infiltration in paw tissues, suppressed gene expressions of p38 and p65, down-regulated the NF-κB and MAPK signaling pathways and reduced protein levels of TNFα, IL-1β and IL-6 in joint tissues of arthritis rats." (PMID 35630747, 2022). "Furthermore, we have previously demonstrated that a more severe inflammation, seen as high levels of IL-6, is associated with lower expression of VPAC1 in PBMCs from patients with early arthritis and, conversely, with increased expression of VPAC2." (PMID 35955723, 2022). "Patients with early arthritis may also benefit from early introduction of anti-IL-6 therapy, as anakinra may be less consistently effective in these cases." (PMID 35268449, 2022). "In three articles, homogeneous doses of extracts (10–50 mg/kg) were shown to decrease the arthritis score; the mechanisms that explain the biological effects include the inhibition of pro-inflammatory cytokines (IL-6, TNF-α) and the increase of antioxidant enzymes (MDA, GSH, SOD)." (PMID 36364420, 2022). "It was stated that the cytokines such as TNF-α, IL-1β, IL-6, IL-8, and IL-18 secreted by B lymphocytes and synovial fibroblasts (SFs) potentially regulate the balance of anti-inflammatory and pro-inflammatory factors during arthritis." (PMID 35877372, 2022). "A high dose of L-pyroglutamate given before inducing CIA could significantly upregulate anti-COII IgG, IL-6, eotaxin, and arthritis score." (PMID 34852827, 2021). "Data from the literature suggest that different cytokine profiles may be responsible for distinct clinical manifestations, as systemic subsets seem to present with high levels of IL-18 and IL-1β while patients with arthritis exhibit higher IL-6 serum levels." (PMID 34203779, 2021). "It has been reported that arthritis-related genes of IL1β, IL6, and TNFα are expressed in the cartilage in AVNFH and could be potential biomarkers for AVNFH." (PMID 34305456, 2021). "IL17RA is a key component required for IL17A activity, and blocking of IL17 binding by IL17RA could inhibit the expression of IL-6 to prevent synovial inflammation in arthritis." (PMID 34305456, 2021). "The arthritis index, ankle joint swelling rate, IL-1β, IL-6, and MCP-1 levels in serum, SA level in liver tissue, and IκB, P-IκB, P65, and P-P65 protein levels in synovial tissues were significantly higher (P < 0.01) in the CIA model compared to the control group." (PMID 34367306, 2021). "In addition, an anti-mouse monoclonal antibody IL-6 inhibited the development of arthritis in the same experimental mouse model." (PMID 33435178, 2021). "The severity of arthritis correlated with serum IL-6 levels." (PMID 33833871, 2021). "Treatment with L. casei or L. acidophilus over a period of 28 days reportedly prevented the development of arthritis in a preclinical model that reduced arthritic scores and proinflammatory cytokines such as IL-17, IL-1β, IL-6, and TNF-α, similar to that of indomethacin treatment." (PMID 34065638, 2021). "Intraperitoneal administration of Fgl1 protein significantly decreased the inflammatory cytokine level (i.e., IL-1β and IL-6) in local paw tissue, and prevented joint inflammation, cellular infiltration, bone deformation and attenuated collagen-induced arthritis progression in vivo." (PMID 34975855, 2021). "Indeed, inhibition of IL-6 signaling with anti-IL-6 receptor antibodies suppressed arthritis, with reduced neutrophil infiltration and NETosis." (PMID 34299252, 2021). "Arthritis manifests with the elevation of pro-inflammatory cytokines such as IL-1, IL-6, and TNF-α." (PMID 33478498, 2021). "Therefore, it seems appropriate to acknowledge the IL-6/STAT3/IL-17/NF-κB signaling cascade as a modulator of arthritis and potential therapeutic target." (PMID 33515210, 2021). "Thus, SFs explant cultures from animals undergoing experimental arthritis were examined for ARNO-dependent expression of IL-6, CCL2 and MMP3." (PMID 35095899, 2021).
Arthritis (continued). "Only a low dose of xylitol given after inducing CIA could significantly upregulate the levels of anti-COII IgG, IL-6, IL-17A, and arthritis score." (PMID 34852827, 2021). "Thus, at 6 week, it is too early to see the effects of proinflammatory factors produced in arthritis lesion on the level of IL-6 in other tissue, especially in gut, via systemic dissemination." (PMID 33076980, 2020). "Analysis of adjuvant-induced arthritis(AIA) in IL6+/+ and IL6−/− mice demonstrated that IL6 deficiency is associated with reduced synovial infiltration and is accompanied by a defect in both CCL2 expression and the recruitment of leukocytes bearing the CCL2 receptor CCR2." (PMID 33126846, 2020). "Gene knockout of both IL-6 and IL-8 has been found to protect against arthritis in animal models." (PMID 32471152, 2020). "However, we did find bilateral hyperalgesia and raised serum cytokines TNFα, IL-7, and IL6 in arthritis mice." (PMID 32471455, 2020). "Interleukin-6 (IL-6) is a ubiquitous pro-inflammatory cytokine of acute inflammation, particularly involved in the synovial hypertrophy, as well as an established therapeutic target for arthritis." (PMID 33182470, 2020). "Indeed, plasma IL-6 levels have been reported to be extremely high in pre-arthritis patients and the CIA model of RA, whereas levels of TNFα tend to decrease with the onset of disease." (PMID 32634159, 2020). "As the result of the ZAP-70 gene mutation in T cells, arthritis occurs spontaneously without LA, while the cellular source of IL-6 in SKG appears to be macrophages which can be affected by the PAMPs released from oral and gut microbiome of the mice." (PMID 33076980, 2020). "In this study, the more efficiency of combination therapy in improving signs of arthritis in AA rats may be due to remarkably reduced IL-6 and IL-17 levels." (PMID 33198544, 2020). "Together with other cytokines such as IL17, both IL6 and TNF are known to induce the RANKL expression that subsequently enhances osteoclastogenesis and bone destruction, and are thus considered pathogenic in S. aureus arthritis." (PMID 32111171, 2020). "An anti-VEGF peptide could decrease the serum level of IL-6 in a collagen-induced arthritis mice model, and alleviate the severity of the disease." (PMID 31757048, 2019). "Application of sCD83 not only reduced the clinical symptoms of arthritis, but also inhibited the antigen-specific T cell proliferation upon mBSA-restimulation and impaired production of key inflammatory effectors, including IL-17A, TNFα, IFNγ, and IL-6." (PMID 31001257, 2019). "This explains our finding of modest but significant elevated expression levels of IL-1, IL-6, CCL3, and MCP1 in the bone marrow cells of KLF2 heterozygous mice after induction of arthritis, which were associated with the formation of marginal erosions found in KLF2+/− mice." (PMID 31426355, 2019). "Concerning the effects of IL-38 on arthritis, the induction of serum-transfer induced arthritis (STIA) in IL-38-deficient mice determines a more severe phenotype and a higher joint expression of IL-1β and IL-6 compared with littermates control." (PMID 30871134, 2019). "Juvenile idiopathic arthritis (JIA) is a heterogeneous disease characterized by the arthritis of unknown origin and IL6 is a known target forJIA." (PMID 31435158, 2019). "Both IL-17 and IL-6 contribute to arthritis development at the early onset of RA." (PMID 31164995, 2019). "Arthritis in TNF-α transgenic mice was not affected by IL-6 deficiency, while CIA was abolished, possibly involving inhibition of Treg differentiation by this cytokine in the latter model." (PMID 30937315, 2019). "Overall, these results suggest that local ice cryotherapy might be more efficient in reducing the synovial IL-6 levels in microcrystal-induced arthritis compared to RA and SpA." (PMID 31362785, 2019). "It is well-established that IL-6 expression is increased in arthritis and peripheral nerve injury." (PMID 32047493, 2019).
Arthritis (continued). "The results indicate that SHW could be used to improving arthritis by reducing inflammatory factors (IL-6 and TNF-alpha)." (PMID 30606189, 2019). "IL-6 exerts various effects on hepatocytes and lymphocytes in acute or chronic inflammatory diseases and anti-IL-6 receptor antibody was developed to treat arthritis and other refractory immune-mediated diseases." (PMID 30177931, 2018). "In addition, IL-6 neutralizing antibodies have been administered to mice in collagen-induced in vivo arthritis models, where they protected the mice from bone lesions and disease progression." (PMID 30671025, 2018). "Our results also demonstrated that UC-MSCs treatment could increase MSCs A20 expression so that was able to inhibit arthritis and reduce the expression of pro-inflammatory cytokine (especially IL-6) in CIA mice." (PMID 29323140, 2018). "Signal blockade of IL-6 or TNFα markedly ameliorates arthritis in KO1 mice." (PMID 29422084, 2018). "Furthermore, the IL-17-triggered positive feedback loop between IL-17 and IL-6 and its downstream effector Stat3 reportedly promotes arthritis development in gp130 mutant F759 mice." (PMID 30361689, 2018). "It has been reported that thymoquinone reduces TNF-α and IL-6 in blood and arthritis tissues." (PMID 30049280, 2018). "Further studies revealed that enhanced arthritis in Smad7 KO CD-1 mice was associated with increased Th1, Th2 and, importantly, Th17 over the Treg immune response with overactive TGF-β/Smad3 and proinflammatory IL-6 signaling in the joint tissues." (PMID 30450102, 2018). "The acute inflammation of arthritis induced by zymosan is IL-6-independent." (PMID 30075804, 2018). "UPIA patients who differentiated into definite arthritis, had significantly higher baseline IL-6 PB levels (9.27 ± 2.36 pg/ml) compared to patients who remained as UPIA (3.49 ± 4.90 pg/ml; p = 0.01), whereas comparable PB VEGF-A and VEGF-D levels were found comparing the two subgroups." (PMID 30018954, 2018). "In addition, the supernatants were collected from each group, and CBAs were used to evaluate the levels of pro-inflammatory factors (IL-17A, TNF-α and IL-6), which are closely related to arthritis progression." (PMID 29370826, 2018). "Similar to CIA, SKG arthritis is dependent on pro-inflammatory cytokines, particularly IL-6." (PMID 28753982, 2017). "Thus, we believe that IL-7, such as TNF-α, IL-6, and IL-1, is a potent factor that can itself induce osteoclasts, suggesting the potential of IL-7 as the “best” therapeutic target for alleviating arthritis by suppressing both inflammation and bone erosion." (PMID 29104576, 2017). "Initial findings in a previous study showed that FTS treatment reduced the clinical arthritis score in the AIA model, and that this treatment was associated with reduced levels of various pro-inflammatory cytokines (IFN-γ, TNF-α, IL-6, and IL-17) in the serum at study end." (PMID 28736556, 2017). "Thus, a positive feedback loop between IL-6 and IL-17, which was triggered by Th17 cells, was responsible for the development of arthritis in gp130 F759 mice." (PMID 28753982, 2017). "Interestingly, platelets activated by pro-inflammatory cytokines (e.g., TNF-α, IL-6) play an important role in the pathogenesis of joint inflammation." (PMID 28247163, 2017). "Thus, we found meloxicam to be the most potent inhibitor in terms of arthritis score, affect on serum IL-6 and IL17 levels and cartilage erosion in CIA mice." (PMID 28887478, 2017). "Tryptase inhibition was effective in inhibiting some inflammatory parameters associated to mBSA/IL-1β-induced arthritis, notably late phase oedema formation and IL-6 production, but not neutrophil infiltration and joint degeneration." (PMID 28587618, 2017). "Collectively, these results suggest dual IL-6/IL-21 inhibition may be a more efficacious therapeutic strategy compared to single cytokine blockade to suppress arthritis development." (PMID 28158305, 2017).